AFP (alpha fetoprotein)
Diseases named in the same sentence as AFP in open-access papers (continued):
Sharing a sentence is not in itself a finding about the gene and the disease.
tumor (continued). "We also found correlations between AFP and baseline features of the tumor." (PMID 38792876, 2024). "In addition, the coexpression of the AQP3 and AQP5 proteins is positively correlated with elevated serum AFP levels, tumor stage, and tumor grade." (PMID 39048663, 2024). "At the multivariate analysis, our results show that in addition to AFP ≥ 1000 ng/mL, tumor size ≥ 5 cm, Child–Pugh functional class B or C, BCLC stage A (early) compared with stage 0 (very early), and malignant PVT were independent risk factors for increased mortality." (PMID 38792876, 2024). "Imaging techniques like ultrasound, CT, and MRI are commonly used, along with blood tests that may include the classical tumor marker—alpha-fetoprotein (AFP)." (PMID 39457573, 2024). "Furthermore, high menin expression is associated with more aggressive tumor phenotypes, higher expression of α-fetoprotein (AFP), and lower overall and tumor-free survival." (PMID 39336822, 2024). "Furthermore, tumor markers such as AFP, CEA, and CA199 often have limited clinical value in PHL diagnosis, as they are frequently negative, except in cases of HCC with slightly elevated AFP levels." (PMID 39411128, 2024). "Subgroup analysis revealed that patients with the maximum tumor diameter greater than 7 cm, AFP > 400ng/ml and the presence of PVTT may benefit more from TLT treatment." (PMID 39411718, 2024). "Both alpha-fetoprotein and H19 expression are potent tumour markers in adult liver tissue." (PMID 38992336, 2024). "c-Myc and c-Met, known regulators in tumor development, are effected by AFP." (PMID 39135041, 2024). "Clinical evaluation of these protein subgroups showed that patients in the G-II subgroup had a higher frequency of tumor thrombus (P-value = 1.2e-04), higher AFP level (P-value = 0.011), and advanced TNM stages (P-value = 0.003) compared to those in the G-I subgroup (Kruskal-Wallis test)." (PMID 38806474, 2024). "Given the ease of peripheral blood sampling, MDSCs could serve as a complementary biomarker to AFP for assessing tumor biology and guiding therapeutic strategies." (PMID 39222024, 2024). "In patients with HCC, a sharp increase in AFP indicates tumor recurrence or metastasis." (PMID 38763973, 2024). "One of the best-characterised tumour markers in HCC is alpha-fetoprotein (AFP)." (PMID 38760445, 2024). "Therefore, investigating the relationship between early AFP response and early tumor progression is essential for optimizing patient management and improving the efficacy of ICI in combination with targeted therapy." (PMID 39767676, 2024). "In addition, the increased levels of tumor markers, such as AFP and CA 15-3, revealed simultaneously in other studies, demonstrate the ability of brown HT to cause malignant changes in mammary tissues." (PMID 39659309, 2024). "By incorporating the protein tumor marker AFP, which retained the benefits of current clinical methods, and employing sWGS to detect the whole genomic CNA and FS profiles, we aimed to detect the genomic‐level changes and to reduce processing time and costs, particularly for analyzing cancer tissue." (PMID 39704423, 2024). "However, the specific relationship between early AFP response and early tumor progression following ICI combined with targeted therapy has not been thoroughly investigated." (PMID 39767676, 2024). "In addition, patients with high APOA2 and low SAMD4B expression levels had larger tumours and higher AFP levels." (PMID 38886351, 2024). "However, some other well-defined adverse clinicopathologic factors were not significantly different between the two ALI groups, such as AFP, tumor number and grade, and vascular invasion." (PMID 38390261, 2024). "In addition, AFP is used for prognostication and selection for liver transplant candidates, as high levels of AFP are correlated with poor differentiation of the tumour and generally poorer clinical outcomes." (PMID 38760445, 2024).
tumor (continued). "Although it may be applicable to tumor markers, AFP has a CLIA 2024 goal of 20 %, a desirable Ricos goal of 21.9 %, and an EFLM minimum goal of 26.5 %." (PMID 39155970, 2024). "In cases of SPN, elevated levels of tumor markers such as alpha-fetoprotein, carcinoembryonic antigen, CA199, CA125, and CA242 may be observed; however, these markers lack specificity for SPNs." (PMID 38870658, 2024). "High AFP levels result from its production by the huge mass of tumor tissue." (PMID 38256600, 2024). "Alpha-fetoprotein is, in fact, an established marker in HCC, being overexpressed in the vast majority of patients and being associated with drug resistance and increased tumor progression." (PMID 38473265, 2024). "Conversely, AFP response may reflect the overall subclinical disease burden and provide further information on the overall improvement in tumor burden." (PMID 38433845, 2024). "ACT-903, an anti-tumor drug developed by Alpha Cancer Technologies Inc., is a conjugate of AFP and maytansine." (PMID 38678117, 2024). "Nevertheless, this study is valuable in that it provided comprehensive clinical information regarding changes in tumor size and the trend in AFP levels and half-life in patients with HH according to the treatment administered, as well as detailed progress of each patient." (PMID 38792380, 2024). "There are histopathological types, such as embryonal carcinoma, that do not secrete tumor markers, as well as immature teratomas that can cause elevated AFP levels and germinomas that can cause mild elevation of HCG." (PMID 38790424, 2024). "Due to the scarcity of liver resources, the process of liver transplantation necessitates doctors to exercise meticulousness in the selection of a suitable liver, taking into consideration many parameters such as tumor stage, AFP level, and cumulative dose of immunosuppressants." (PMID 39654222, 2024). "In our study, only AFP was the independent risk factor in clinical characteristics for predicting the status of MVI, which was consistent with the previous study, suggesting that high levels of AFP can respond to tumor cell invasion." (PMID 39184049, 2024). "The clinical basis for identifying a secreting tumor is AFP >10 IU/L or β-HCG >50 IU/L." (PMID 38665953, 2024). "In addition, MNDA as an independent prognostic indicator was superior to most clinical markers (AFP level, tumor diameter, number of tumors, BCLC stage, and presence of MVI)." (PMID 38904028, 2024). "In addition, we also analyzed the effects of taking TCM on the 1-year MVI incidence of HCC patients with different etiology, tumor stage, serum AFP level, liver functions and treatment type." (PMID 38464727, 2024). "In addition, we established a nomogram that included AFP level, tumour size, tumour margin, and APE to predict MVI with high accuracy and was validated internally and externally." (PMID 38281008, 2024). "Exosomes derived from α-fetoprotein (AFP)-expressing DCs could suppress tumour progression in mice with ectopic, orthotopic and carcinogen-induced HCC tumours by remodelling the tumour immune microenvironment." (PMID 38302430, 2024). "Similarly, the Univariate analysis for PFS highlighted AFP levels, tumor number, macrovascular invasion, and downstaging liver resection as risk factors." (PMID 39763684, 2024). "Therefore, we divided these patients into different subgroups according to the age, tumor size, T stage, grade, AFP level and surgery, to further confirm the effectiveness of the nomogram." (PMID 37067674, 2024). "Additionally, certain tumor properties such as tumor number, type, and metastasis were associated with abnormal elevation of PIVKA-II and AFP levels, although this association was only significant in univariate analysis." (PMID 39432605, 2024).
tumor (continued). "The prognostic factors relevant for HCC in the context of LT were tumour morphology, tumour biology, tumour grade, cancer-related symptoms, the dynamics of the tumour biomarker alpha-fetoprotein, the response to bridging therapy and the presence of angioinvasion." (PMID 38473282, 2024). "On day 14 of chemotherapy, tumor markers had normalized (CSF β-hCG < 1 IU/L and AFP 0.07 ng/mL)." (PMID 39568077, 2024). "Thus, the data obtained in this model are also consistent with the assumption that the iRGD-induced tumour-blood transport of AFP depends on the concentration gradient for AFP." (PMID 38889481, 2024). "AFP is a specific tumor marker for HCC with a specificity of up to 93.3%for early diagnosis." (PMID 39090609, 2024). "Tumor marker levels, including AFP, CEA, and CA19-9, were typically within the normal range." (PMID 39640280, 2024). "Alpha‐fetoprotein (AFP) vaccines, including DC vaccines, DNA vaccines and peptide vaccines, introduce AFP epitope peptides to APCs, leading to the generation of multiple AFP‐specific CTLs and induction of tumour immunity." (PMID 38935536, 2024). "Combining multiple strategies, like targeting AFP and its downstream pathways with immunotherapy and radiotherapy, may more effectively control tumor growth and invasion." (PMID 38660138, 2024). "The nomogram incorporates tumor features (AFP level and tumor size) and recipient morphological characteristics (size and weight), as well as the waiting time on the list, providing a comprehensive tool for predicting the 10-year survival in this specific LT setting." (PMID 38791881, 2024). "Diagnosis hinges upon recognizing the broad clinical presentation, employing imaging techniques (such as ultrasound and MRI), evaluating tumor markers (alpha-fetoprotein and beta-human chorionic gonadotropin), and conducting histopathological examinations where necessary." (PMID 38380211, 2024). "Notably, BCLC Class C, high AFP levels, larger tumor size, and receiving TACE combined with both sorafenib and ICIs were associated with better PFS outcomes." (PMID 39062006, 2024). "Thirdly, we didn’t measure the lymphocyte density in tumor tissues to explore their correlation with AFP levels, the basic experiments with humanized animal model should be performed to evaluate the changes of tumor microenvironment (especially immune cells) upon AFP induction." (PMID 38408930, 2024). "In addition, normalization of the serum levels of the tumor markers AFP and DCP was observed following atezo/bev therapy in all cases, except one that was not mentioned." (PMID 38071671, 2024). "The current evaluation of transplantability of HCC patients is based on morphological criteria, with AFP as the only surrogate of tumor biology, while the number of treatments needed to obtain the downstaging and the duration of response are used as a surrogate of tumor behavior." (PMID 38473400, 2024). "Since AFP can inhibit the maturation of DCs, it can promote tumor immune escape." (PMID 38660138, 2024). "According to univariate and multivariate Cox regression analysis, we found that 5 variables including beyond Milan criteria, pre-transplant AFP greater than 400, poor tumour differentiation, microvascular invasion and HBV reactivation were independent risk factors for post-transplant OS." (PMID 38348848, 2024). "The survival of patients with HCC is influenced by a variety of factors, including age, tumor characteristics (such as size, number, vascular invasion, and extrahepatic spread), serum alpha-fetoprotein (AFP) levels, physical condition, and liver functional reserve." (PMID 39796655, 2024).
tumor (continued). "Tumour size (OR: 1.061; 95% CI: 1.020–1.104; p = 0.003), AFP level (OR: 2.008; 95% CI: 1.144–23.526; p = 0.015), tumour margin (OR: 2.645; 95% CI: 0.1211–5.775; p = 0.015), and APE (OR: 2.556; 95% CI: 1.085–6.021; p = 0.032) were independent predictors of MVI in multivariate analysis." (PMID 38281008, 2024). "Tumor markers: Tumor markers, such as AFP and β-hCG, are important prognostic indicators." (PMID 38380211, 2024). "However, tumor number, pre-transplant AFP level, proportion of group within Milan criteria, and treatment including chemotherapy and cryoablation were similar among the three groups." (PMID 38408903, 2024). "The diagnosis is made by US, CT and MRI and analysis of serum levels of tumour markers such as AFP, CA 125 and CA 19–9, which have demonstrated specificity and sensitivity in clinical use and are useful for monitoring disease progression, and histopathological examination." (PMID 39001474, 2024). "Furthermore, AFP can undermine macrophage-mediated phagocytosis of tumor cells by interacting with macrophage receptors and inducing tumor immune escape." (PMID 38660138, 2024). "The AFP tumor marker was significantly elevated at 19,420.0 ng/mL." (PMID 39697937, 2024). "Furthermore, biomarkers such as circulating tumor DNA assays and circulating tumor cells have also been noted in the improvement of AFP prediction performance." (PMID 38476367, 2024). "Furthermore, numerous studies have demonstrated the tumor-promoting effects of AFP, which include inhibition of apoptosis, stimulation of proliferation, and enhancement of migration, invasion, and metastasis." (PMID 39583507, 2024). "Tumor marker levels revealed only an elevated level of alpha-fetoprotein (AFP: 5304.0 ng/mL)." (PMID 38504916, 2024). "The RELAPSE Score factors in pre-transplant NLR, pre-transplant maximum AFP, micro- and macro-vascular invasion on explant pathology, maximum tumor diameter on explant, and explant tumor grade, and demonstrated good discrimination (0.75 – 0.77) upon external validation." (PMID 39085572, 2024). "Our univariable Cox analysis revealed that ALB < 35 g/L, AFP ≥ 200 ng/mL, Child-Pugh B, BCLC A, larger tumor diameter, MVI, Edmondson-Steiner III-IV, NAR, and surgical margin < 1 cm were significantly associated with tumor recurrence (all P < 0.05)." (PMID 39090609, 2024). "It has also been suggested that AFP-induced tumor stem cells can secrete AFP." (PMID 38660138, 2024). "Serum tumor markers, including alpha-fetoprotein (AFP) and beta subunit of human chorionic gonadotropin (β-hCG), may be within normal limits, further complicating diagnosis." (PMID 38817478, 2024). "Diagnosis starts with identifying its clinical features and associating it with age-related malignancy in this population and the use of tumor-associated markers (CA-125, CA 19-E4, CEA, alpha-fetoprotein (AFP), Inhibin, and PSA) for the culprit underlying malignancy." (PMID 38939277, 2024). "The authors found that a high density of CD68 TAMs in the IT region was also associated with high AFP levels, large tumor size, absence of encapsulation, presence of vascular invasion and a higher tumor-node-metastasis (TNM) stage." (PMID 38997297, 2024). "The study identified five predictors of overall survival (OS) post-transplant in HBV-related HCC patients: variables beyond the Milan criteria, pre-transplant AFP (alpha-fetoprotein) levels exceeding 400, poor tumor differentiation, microvascular invasion, and HBV reactivation." (PMID 39143716, 2024). "Some studies proposed that AFP may regulate the growth of tumor cells by mechanisms, including apoptotic regulation and cytoplasmic signaling modulation." (PMID 38713414, 2024). "Additionally, tumor markers, including carcinoembryonic antigen (CEA), glycan antigen, cytokeratin 19 fragment, alpha-fetoprotein (AFP), and squamous cell carcinoma-associated antigen, were all within normal ranges." (PMID 39464706, 2024).
tumor (continued). "Additionally, this immunosensor shows excellent selectivity for PSA, exhibiting minimal affinity for common tumour marker proteins such as L-tryptophan, AFP, and CEA." (PMID 39686170, 2024). "Notably, elevated frequencies of mMDSCs were associated with higher AFP levels, elevated PIVKA‐II values, advanced BCLC stages, larger tumor sizes, and the presence of portal vein invasion or distant metastasis." (PMID 39222024, 2024). "Rats that were fed an HSHF diet for either 9 or 12 weeks displayed a notable increase in serum liver enzymes (ALT, AST, ALP, albumin, GGT, total bilirubin, direct bilirubin) and lipid profile (TC, TG, and LDL-C), along with elevated levels of the AFP tumor marker." (PMID 39182075, 2024). "Furthermore, the authors showed that tumor size, AFP protein level, microvascular invasion, and miR-221 were significantly correlated with DFS and OS." (PMID 39596302, 2024). "Her serum tumor markers (AFP, CA-125, and hCG) were all normal on her final follow-up in July 2024." (PMID 39734342, 2024). "Despite the limited immunogenicity of AFP, it can provoke immune evasion by suppressing the function of DCs, NK cells, and T lymphocytes, forming an immunosuppressive microenvironment, thereby promoting tumor progression." (PMID 38660138, 2024). "Although DS is widely accepted as a method for expanding LT indication in HCC, unresolved issues remain, such as establishing the limits on tumor burden and AFP levels for DS candidacy, as well as defining the criteria for successful DS in terms of the extent and duration of tumor response." (PMID 39272917, 2024). "Additionally, multifactorial analysis confirmed that HBV infection, a tumor diameter ≥3 cm, an AFP concentration ≥ 400 ng/mL, and early recurrence were independent risk factors for poor OS (p < .05)." (PMID 38488487, 2024). "TAP is an abnormal product of tumor metabolism, which is similar to how AFP may be a biomarker; it may be a passenger product of tumorigenesis, and the sexual hormone as basis for individual differences naturally exists in the prerequisite of the tumor." (PMID 40046668, 2024). "AFP levels decreased and the tumor size was reduced by 17.3 % at 2.1 months." (PMID 39108869, 2024). "Moreover, baseline tumor biomarker (such as AFP) levels are helpful to monitor the response to ablation." (PMID 38495485, 2024). "Serum tumor marker detection showed hCG was 78.9 mIU/mL, and AFP was 1.2 ng/mL." (PMID 38394502, 2024). "Moreover, serum tumor markers are useless, because alpha fetoprotein (AFP) was almost within normal limits in the reported cases." (PMID 39272784, 2024). "The proliferation of AFP-TCR-T after HepG2 tumor stimulation was further monitored." (PMID 38643203, 2024). "Patients frequently present with abdominal pain, malaise, weight loss, or a palpable abdominal mass or hepatomegaly; liver function tests may be normal or mildly elevated, and serum alpha-fetoprotein (AFP) is useless as a tumor marker." (PMID 39020233, 2024). "Similar to iRGD-induced tumour import, the iRGD-induced elevation of the blood AFP concentration was blocked by a neutralizing anti-NRP-1 antibody and the timing of the two effects showed similar rapid onsets, indicating a close relationship between the two transport processes." (PMID 38889481, 2024). "Tumor markers were normalized to 3.4 ng/ml AFP and 18 U/ml CA19-9." (PMID 39734687, 2024). "Moreover, the tumor organoids expressed specific markers for hepatocytes (AFP/hepatocyte nuclear factor 4α) and cholangiocytes (epithelial cell adhesion molecule [EpCAM]/cytokeratin 19)." (PMID 39192365, 2024). "Interestingly, with respect to tumor markers, AFP was one of the independent predictors for survival, whereas PIVKA-II was one for the changes in SMI during AB or LEN." (PMID 38275883, 2024).